LINC00460 (long independently transcribed non-coding RNA 460)
Diseases named in the same sentence as LINC00460 in open-access papers (continued):
Sharing a sentence is not in itself a finding about the gene and the disease.
esophageal cancer (4 papers, 2018 to 2023). A primary or metastatic malignant neoplasm involving the esophagus. "LINC00460 can also function as a molecular sponge to adsorb miR-1224-5p, thereby promoting esophageal cancer (ESCA) metastasis and progression." (PMID 37251440, 2023). "In this study, we analyzed two upregulated lncRNAs DUXAP8 and LINC00460 co‐expressed PCGs in esophageal cancer, and found that DUXAP8 associated PCGs are enriched in cell division and cell cycle, while LINC00460 associated PCGs are enriched in focal adhesion and cell‐cell junction processes." (PMID 29926523, 2018). "Furthermore, DUXAP8 is positively related to MAGEA4, GABRA3 expression, and negatively related to INPP5A, TIMP4 expression in esophageal cancer; LINC00460 is positively related to ITGA3, LAMC2 expression, and negatively related to FOXO4, KLF15 expression in esophageal cancer." (PMID 29926523, 2018). "Interestingly, these pathways are closely associated with tumor cells proliferation and invasion, suggesting that DUXAP8 and LINC00460 might play important roles in esophageal cancer tumorigenesis and progression." (PMID 29926523, 2018).
glioma (4 papers, 2020 to 2024). A benign or malignant brain and spinal cord tumor that arises from glial cells (astrocytes, oligodendrocytes, ependymal cells). "LINC00460 over-expression is strongly associated with poor survival rates in different tumors, such as lung, ovary, larynx, nasopharynx, head and neck, meningioma, kidney, thyroid, colorectal, glioma, osteosarcoma, bladder and cervix." (PMID 33912452, 2021). "LINC00460 was found to be overexpressed in five different types of cancer versus normal tissue (BRCA, COAD, HNSC, PAAD, and READ), while in two central nervous system cancers, LINC00460 showed low expression, compared to normal tissue counterparts (GBM and LGG), and a lack of expression in LAML33." (PMID 38233470, 2024).
hepatocellular carcinoma (4 papers, 2021 to 2022). A malignant tumor that arises from hepatocytes. "It is also found that LINC00460 overexpression promotes hepatocellular carcinoma progression." (PMID 33345740, 2021).
papillary thyroid carcinoma (4 papers, 2019 to 2022). "This study suggested that LINC00460 was upregulated in papillary thyroid cancer tissues and cells and knockdown of LINC00460 inhibited proliferation, migration, invation and epithelial-to-mesenchymal transition (EMT) of PTC cells." (PMID 31870440, 2019). "LncRNA LINC00460 has been proved to play roles in the oncogenesis and progression of various tumors, including papillary thyroid cancer." (PMID 31870440, 2019). "Overall, LINC00460 promoted the papillary thyroid cancer progression by regulating LINC00460/miR-485-5p/Raf1 axis, which might provide novel biomarkers for PTC treatment." (PMID 31870440, 2019).
cervical cancer (3 papers, 2021 to 2025). A primary or metastatic malignant neoplasm involving the cervix. "Numerous studies have highlighted the involvement of LINC00460 in the development of various cancers, yet its function in cervical cancer remains uncertain." (PMID 41261348, 2025). "LINC00460 was usually upregulated in cervical cancer tissues and cell lines, knockdown of LINC00460 restrain cervical cancer cell growth and invasion in vitro and attenuated tumorigenesis in vivo." (PMID 33517850, 2021). "Our research uncovers a new negative regulatory relationship involving LINC00460 and the expression of HPV E6/E7 in cervical cancer cells that are HPV‐positive, which is different from the known oncogenic function of LINC00460." (PMID 41261348, 2025).
clear cell renal cell carcinoma (2 papers, 2021 to 2022). "LINC00460 has been extensively studied in cancer and has been shown in several studies to be a prognostic target in renal clear cell carcinoma." (PMID 36104748, 2022).
meningioma (2 papers, 2019 to 2021). A generally slow growing tumor attached to the dura mater. "It has been reported that LINC00460 is found to be overexpressed in human cancer, such as meningioma and laryngeal squamous cell carcinoma." (PMID 30601026, 2019). "Meanwhile, SNHG1, LINC00702, LINC00460, and MEG3 have been found to partake in the pathogenesis of meningioma." (PMID 34885097, 2021).
osteosarcoma (2 papers, 2020 to 2022). A usually aggressive malignant bone-forming mesenchymal neoplasm, predominantly affecting adolescents and young adults. "LINC00460 has been reported to be positively associated with lymph node and distant metastases as well as TNM stage in diverse malignancies, including bladder, colorectal, esophageal, gastric, head and neck, liver and papillary thyroid cancers, as well as osteosarcoma." (PMID 35906593, 2022).
pancreatic adenocarcinoma (2 papers, 2021 to 2022). "Based on TCGA database, LINC00460 expression in pancreatic adenocarcinoma (PAAD) and normal tissues was analyzed." (PMID 36482354, 2022).
kidney cancer (1 paper, 2018). Primary or metastatic malignant neoplasm involving the kidney. "For instance, LINC00460 is upregulated in HNSCC and kidney cancer, and its elevated expression is associated with poorer survival." (PMID 30069008, 2018).
metastasis (1 paper, 2022). The spread or migration of cancer cells from one part of the body (where they first appeared) to another. "Univariate and multivariate regression analyses demonstrated that higher expression of LINC00460 and MCM4 was significantly associated with tumor size, lymph node metastasis, distant metastasis and TNM stage." (PMID 36291859, 2022).
rectal cancer (1 paper, 2023). A primary or metastatic malignant neoplasm that affects the rectum. "The findings of this study provide novel insights into the mechanisms underlying CSCC, and LINC00460 might serve as a potential novel diagnostic and therapeutic target in rectal cancer treatment." (PMID 36513874, 2023).
triple-negative breast carcinoma (1 paper, 2021). An invasive breast carcinoma which is negative for expression of estrogen receptor (ER), progesterone receptor (PR), and human epidermal growth factor receptor 2 (HER2). "To further characterize LINC00460 association with aggressive BRCA, we analyzed its expression in Lehman refined triple negative breast cancer classification (TNBCtype4)." (PMID 33912452, 2021).
tumor (35 papers, 2017 to 2025). "LINC00460: Recently identified as a significant regulator in various cancers, LINC00460 is generally associated with aggressive tumour phenotypes, including larger tumour size, advanced clinical stage, lymph node metastasis and reduced overall survival." (PMID 41261348, 2025). "This thesis is supported by the results of studies demonstrating that the inhibition/down-regulation of LINC00460 was associated with hampered tumour cell proliferation and invasion in various cancers, such as colorectal cancer, gastric cancer, etc.." (PMID 36614082, 2022). "LINC00460 over-expression was significantly associated with advanced and locally advanced tumor clinical stages in three distinct cancers: LUSC, LUAD and KIRC (ANOVA; p<0.05)." (PMID 33912452, 2021). "During our analysis, we examined the associations between LINC00460, LINC00941, RP11-357H14.17, CTC-241F20.4, clinical features, and tumor infiltration levels in the TCGA-HNSC dataset." (PMID 38553620, 2024). "MYC, CD47 and PD-L1 are considered to generate an immunosuppressive “cold” tumor microenvironment in CRC, providing insight into why LINC00460 induces immune escape and the shaping of suppressive tumor immune microenvironment." (PMID 39135122, 2024). "The growth curves and tumor volume and weight showed that overexpression of LINC00460 significantly promoted the subcutaneous tumor, and knockdown of LINC00460 inhibited the tumor growth." (PMID 39135122, 2024). "The results were identical to the in vitro experiments, and the tumor volume and weight of the LINC00460 down-regulated group were reduced compared with the control group, whereas overexpression of LINC00460 promoted tumor growth rate." (PMID 37786443, 2023). "LINC00460 has been reported to participate in proliferation, metastasis, and invasion of various tumor types." (PMID 37786443, 2023). "The tumour size was more significantly reduced in the LINC00460 knockdown group than in the control group." (PMID 36513874, 2023). "Univariate and multivariate regression analyses demonstrated that higher expressions of LINC00460 and MCM4 were significantly associated with tumor size, lymph node metastasis, distant metastasis and TNM stage." (PMID 36291859, 2022). "Knockdown of LINC00460 noticeable suppressed proliferation of tumor cells, as presented by the markedly reduced tumor volume, size and weights in the knockdown group." (PMID 35912013, 2022). "LINC00460 knockdown suppressed cell proliferation, migration, and invasion, facilitated cell apoptosis and G0/G1 phase arrest, and inhibited the tumor growth through anti-PD-1 therapy." (PMID 36482354, 2022). "The expression of LINC00460 is up-regulated in gefitinib-resistant NSCLC tissues and cells and is closely associated with advanced tumor stage and poor clinical prognosis." (PMID 36291859, 2022). "The expression levels of four FRlncRNAs were verified by qRT-PCR from twenty ccRCC patients, which found that LINC01550 and EPB41L4A-DT in tumor tissues were downregulated, while LINC00460 and LINC00944 were upregulated." (PMID 35350243, 2022). "Altogether, these observations suggest that LINC00460 expression is generally related to intrinsically aggressive tumor phenotypes, as shown for HNSC, LUSC, LUAD, KIRC and basal-like BRCA." (PMID 33912452, 2021). "Consistent with these previous data, our results showed that LINC00460 KD and OE respectively reduced or increased tumor cell growth, migration, and invasion abilities." (PMID 33526059, 2021). "LINC00460 overexpression sufficiently induced the epithelial–mesenchymal transition and promoted tumor cell proliferation, migration, and invasion in vitro and tumor growth and metastasis in vivo." (PMID 33526059, 2021). "Our data also showed that LINC00460 downregulation suppressed tumor growth and lung metastasis in a xenograft mouse model." (PMID 33526059, 2021).
tumor (continued). "We also investigated some clinical pathological status of patients with different expression levels of LINC00460 and the data showed that LINC00460 expression was significantly higher in patients with advanced tumor node metastasis (TNM) stage." (PMID 31870440, 2019). "Knockdown of LINC00460 by siRNA treatment significantly decreased tumor growth, as shown by the significantly reduced tumor volumes and weights in the knockdown group compared with the control group." (PMID 31429766, 2019). "The results revealed that LINC00460 expression was significantly increased in PTC tissues compared with the adjacent non-tumor tissues." (PMID 31870440, 2019). "The overexpression of LINC00460 in xenograft tumor tissues was confirmed by qRT-PCR, and the results of H&E and Ki-67 staining further confirmed the alterations in tumor formation." (PMID 31429766, 2019). "High levels of LINC00460 and PRDX1 expression were positively associated with lymph metastasis, pathological differentiation and tumor size in HNSCC patients." (PMID 31429766, 2019). "Our research indicated that linc00460 was overexpressed in the majorityof tumor tissues and ESCC cell lines." (PMID 28939763, 2017). "Taken together, these observations indicate that LINC00460 may play a role as a tumor promoter and may serve as a novel prognostic marker in CRC." (PMID 39135122, 2024). "And LINC00460 promotes CRC tumor proliferation and metastasis through immune escape." (PMID 39135122, 2024). "In vivo, LINC00460 silencing significantly decreased tumour growth and metastasis." (PMID 36513874, 2023). "LINC00460 has been identified as an oncogene in various tumours." (PMID 36513874, 2023). "As expected, LINC00460 knockdown decreased the LINC00460 level in xenograft tumour tissues." (PMID 36513874, 2023). "The effect of LINC00460 knockdown on the growth of tumor xenograft was also explored." (PMID 36482354, 2022). "Moreover, Linc00460 has been found to serve as a ceRNA targeting a number of tumor suppressor miRNAs and finally leading to oncogenesis." (PMID 36139687, 2022). "In addition, LINC00460 is also overexpressed in these tumor tissues compared with adjacent normal tissues." (PMID 35906593, 2022). "The molecular mechanism, by which LINC00460 influences the tumor microenvironment and regulates Treg cells remains unknown." (PMID 34880875, 2021). "Moreover, the LINC00460 level is positively related to tumor size, and predicts poor survival of PC patients." (PMID 33345740, 2021). "The expression of LINC00460 in NPC is significantly higher than that in non-tumor tissues." (PMID 34722295, 2021). "These interactions suggest that LINC00460 is involved in important cancer-related processes like tumor differentiation, hormonal status and HER2 expression in mexican BRCA patients, although the exact related mechanisms remain unclear." (PMID 33912452, 2021). "In the BRCA model, LINC00460 expression is associated with the phenotypic makeup of the tumor, where overexpression of LINC00460 is associated with a negative result to hormone receptors (ER and PR) when subject to IHC." (PMID 33912452, 2021). "In this report, we identified two novel tumor types from TCGA with LINC00460 deregulation." (PMID 33912452, 2021). "LINC00460 expression was evaluated in 31 tumor types and normal tissues included in TCGA database." (PMID 33912452, 2021). "Furthermore, the expression of LINC00460 in xenograft tumor tissues was confirmed by qRT-PCR, which showed that LINC00460 expression was significantly decreased in si-LINC00460-treated subcutaneous xenografts compared to control groups." (PMID 31429766, 2019). "LINC00460 expression was positively associated with the pathological differentiation of tumors and with lymph node metastasis (p < 0.05), whereas PRDX1 expression was positively associated with tumor size (p < 0.05)." (PMID 31429766, 2019).
tumor (continued). "Finally, LINC00460 may affect CRC tumor immunity through other pathways, and we have already evidenced some clues and planned to continue this study." (PMID 39135122, 2024). "In addition, the results of qRT-PCR displayed that in comparison to the adjacent tissues, LINC00460 expression was significantly up-regulated in tumor tissues (P < 0.01), and was also higher in lymph node metastasis of PC patients than that of non-metastasis patients (P < 0.01)." (PMID 36482354, 2022). "Moreover, in vivo experiments have shown that Linc00337, Linc00460, Linc00518, Linc00922, Linc01119, and Linc02163 induce tumor growth and metastasis in vivo which suggests that they could be potential targets for developing novel anti-metastatic therapeutics." (PMID 36139687, 2022). "In addition, the LINC00460 promotes tumor progression through sponge miR-4443 in HNSCC." (PMID 33995377, 2021). "Overexpression of LINC00460 promoted CRC cell immune escape and remodeled a suppressive tumor immune microenvironment, thereby promoting CRC proliferation and metastasis." (PMID 39135122, 2024). "In the in vitro and in vivo experiments, LINC00460 depletion suppressed CSCC cell viability, invasiveness, and migratory potential and tumour growth and metastasis." (PMID 36513874, 2023). "The expression of LINC00460/EME1/HNRNPAB/PLAUR and SEMA3A was higher in most tumour tissues, including LUAD, than in the corresponding control tissues (P < 0.001)." (PMID 36091160, 2022). "The expression levels of LINC00460, LINC00944, LINC01550, and EPB41L4A-DT differed across the four stages, suggesting that four FRlncRNAs were closely related to the tumor stage." (PMID 35350243, 2022). "We suggest that LINC00460 is related with good prognosis in TNBC/basal-like due to its potential relation with these genes and with the presence of tumor-infiltrating lymphocytes (TILs), as shown in our samples." (PMID 33912452, 2021). "We performed xenograft experiments and assessed the effects of LINC00460 and HMGA1 in LINC00460 knockdown CRC cells by using nude mice to demonstrate their effects on tumor growth in vivo." (PMID 33526059, 2021). "We validated the global and CpG island methylation of LINC00460 in the GEO and CCLE databases to further reveal its abnormal regulation and their potential role in tumor formation." (PMID 31632435, 2019). "LINC00460 expression in HNSCC was correlated with lymph node metastasis and pathological differentiation, while PRDX1 expression was correlated with tumor size." (PMID 31429766, 2019). "Therefore, from the 77 epithelial lncRNAs which were upregulated in tumor samples we prioritized 11 candidates: AC016735.1, AC123023.1, BBOX1−AS1, CASC19, LINC00659, FEZF1−AS1, LINC00460, RP11−595B24.2, RP11−796E10.1, RP5−940J5.9 and RP11−350J20.12." (PMID 38740871, 2024). "Furthermore, we analyzed the expression of ceRNAs in tumour and control samples using TCGA, GTEx, and CPTAC databases and found that the expressions of LINC00460/EME1/HNRNPAB/PLAUR/SEMA3A were significantly higher in LUAD tissues." (PMID 36091160, 2022). "Besides survival data, other clinical features including tumor size, histological grade, differentiation degree, lymph node metastasis and TNM stage, are related to LINC00460 expression." (PMID 35906593, 2022). "Our findings showed that LINC00460 expression increased in human CRC, and high LINC00460 expression was correlated with clinicopathological parameters, such as TNM stage, lymph node metastasis, metastasis, and tumor size." (PMID 33526059, 2021). "We found that LINC00460 was deregulated in seven different tumor types in the TCGA database, including two not previously reported tumors, namely LGG and GBM." (PMID 33912452, 2021). "We identified two novel (not previously reported) tumor types from the TCGA cohort with LINC00460 deregulation." (PMID 33912452, 2021).
tumor (continued). "Compared with that in the normal group, the LINC00460 in tumor tissue was significantly hypomethylated, which was negatively correlated with its expression." (PMID 31632435, 2019). "In addition, LINC00460 overexpression is correlated with further aggressive tumor phenotypes, such as HPV negative HNSC (TCGA: Mann-Whitney U, p< 0.05." (PMID 33912452, 2021).